VIM (vimentin)
Diseases named in the same sentence as VIM in open-access papers (continued):
Sharing a sentence is not in itself a finding about the gene and the disease.
oral squamous cell carcinoma (28 papers, 2014 to 2026). "In oral squamous cell carcinoma, tumor buds showed loss of membranous localization of E-cadherin and increased cytoplasmic levels of vimentin, at both cell population and single-cell level." (PMID 27136592, 2016). "JMJD5 was exhibited to be vital for sustaining cell migration and invasion, and the depletion of JMJD5 increased E-cadherin expression patterns and diminished N-cadherin and Vimentin expression in oral squamous cell carcinoma cells." (PMID 38166895, 2024). "Up to our knowledge, this is the first report to describe the status of the vimentin expression in saliva samples from precancer and cancer patients with oral squamous cell carcinoma." (PMID 35498535, 2022). "A previous study demonstrated that bLF treatment increases expression of E-cadherin but decreases that of vimentin in an oral squamous cell carcinoma line, HOC313, in which the EMT signal was induced, resulting in an inhibition of EMT." (PMID 36199689, 2022). "Recent study highlighted that MICAL1 deficiency in oral squamous cell carcinoma arrested MMP9 secretion, vimentin, and E-cadherin levels, consistent with increased N-cadherin." (PMID 31019460, 2019). "The relationship between the PI3K/AKT signaling axis has demonstrated the essential regulatory role of this pathway in EMT and the AKT inhibition induced the expression of E-cadherin and beta-catenin, reduce that of Vimentin, restored their epithelial morphology of oral squamous cell carcinoma." (PMID 39950162, 2025). "In addition, the suppression of vimentin in oral squamous cell carcinoma cells corresponds with the depletion of KRT14 and KRT5 and reduced tumorigenicity, potentially through vimentin-mediated ΔNp63 silencing, as an upstream regulator of KRT14." (PMID 39408880, 2024). "SEVs originating from oral squamous cell carcinoma cells suffering from hypoxia contain miR-21, one of the most dramatically elevated miRs in hypoxic setting conditions, which increases expressions of SNAIL and vimentin while decreasing expression of E-cadherin in oral squamous cell carcinoma cells." (PMID 38243280, 2024). "Therefore, it is of interest to document the molecular docking analysis of proflavin with the Wnt pathway targets (GSK3β, β-catenin, and VIM)for oral squamous cell carcinoma (OSCC)." (PMID 37822816, 2023). "Similarly, oral squamous cell carcinoma cells formed fewer colonies in soft agar and were less capable of invading Matrigel upon vimentin knock-down." (PMID 31940801, 2020). "However, in a study using oral squamous cell carcinoma cells, authors showed that knock-down of vimentin leads to an increase in β4-integrin levels, and a more adherent behavior when cells were grown on laminin-5." (PMID 31940801, 2020). "Although tumor buds of breast carcinoma display higher levels of vimentin, and oral squamous cell carcinoma tumor buds have significantly upregulated fibronectin, only a fraction of tumor samples of oral squamous cell carcinoma underwent a full ‘cadherin switch’ from E-cadherin to N-cadherin." (PMID 27136592, 2016). "Silencing TET1 increases cisplatin sensitivity by altering the expression of multiple genes in various pathological conditions including vimentin in OVCA, and o6-methylguanine-DNA methyltransferase (MGMT) in oral squamous cell carcinoma (OSCC)." (PMID 38216951, 2024). "Another study shows that infection of Porphyromonas gingivalis increases the aggressiveness, metastasis, and viability of oral squamous cell carcinoma (OSCC) through the induction of canonical EMT markers, MMP-9 and vimentin." (PMID 34827233, 2021). "Previous laser capture microdissection studies in both CRC and oral squamous cell carcinomas show that tumor buds over-express EMT-related genes such as ZEB1, ZEB2, DES, TGFB3, and VIM in comparison to the main tumor mass." (PMID 31316988, 2019).
oral squamous cell carcinoma (continued). "In this study, we studied the immunohistochemical expression of vimentin, β-catenin and E-cadherin in oral squamous cell carcinoma with and without lymph node metastasis." (PMID 25047112, 2014).
thyroid cancer (28 papers, 2011 to 2025). "Given that tumor metastasis is a leading cause of death in thyroid cancers, we next tested the expression of the EMT marker E‐cadherin and Vimentin in C643, 8505C, and K1 by western blot assays." (PMID 34264510, 2022). "The findings showed that overexpression of LKB1 exhibited a remarkable increase of mRNA and protein levels of E-Ca, whereas a decrease of N-Ca and vimentin expressions in thyroid cancer TPC-1 and BCPAP cells." (PMID 35912012, 2022). "Quantitative analysis with vimentin band intensities revealed increased expression levels in the 3D spheroid culture environment in all thyroid cancer cell lines (BHP10-3SCp: 0.22 ± 0.04, 8505C: 0.82 ± 0.10, Hth7: 0.24 ± 0.16 and SW1736: 0.21 ± 0.56)." (PMID 36428988, 2022). "E-cadherin, as an epithelial marker, was more predominant than vimentin in thyroid cancer cell lines under 3D spheroid culture condition." (PMID 36428988, 2022). "Overexpression of CTSB in thyroid cancer cell lines activated cell migration by increasing the expression of vimentin and Snail, while its siRNA-mediated silencing inhibited cell migration by decreasing vimentin and Snail expression." (PMID 33333840, 2020). "We similarly demonstrate that low levels of CTSB inhibit cell migration through decreased expression of vimentin or Snail in thyroid cancer cell lines." (PMID 33333840, 2020). "We also demonstrated that TGF-β1 or over-expression of Snail dramatically increased the mesenchymal marker vimentin and stem cell markers in thyroid cancer cells derived from BRAFV600E mice." (PMID 25076938, 2014). "The data demonstrated that while E-cadherin was well expressed in normal thyroid tissue, its expression was markedly decreased and vimentin expression up-regulated in the thyroid carcinomas from the transgenic mice over-expressing BRAFV600E." (PMID 25076938, 2014). "Although both cytokeratin-18 and vimentin expressions were observed even in undifferentiated thyroid cancer cell lines, the cytokeratin-18 expression was lost in the SAGM-grown cells." (PMID 21556376, 2011). "Likewise, a study in thyroid cancer cells also demonstrated similar data, where PD-L1 was shown to repress E-cadherin expression, upregulate vimentin, and promote EMT." (PMID 38431613, 2024). "Our results were consistent with those of a previous study showing that KLF5 regulates E-cadherin expression by binding directly to the slug promoter in immortalized mammary epithelial cells and enhances vimentin expression via activation of the nuclear factor-kB pathway in thyroid cancer cells." (PMID 36142408, 2022). "KA could significantly up-regulate the expression of E-cadherin and down-regulate the expression of Vimentin, so we speculated that KA could effectively inhibit the invasion and metastasis of thyroid cancer." (PMID 34264510, 2022). "The mechanisms of CTSB action in thyroid cancer are unknown and our investigation of the same revealed that CTSB overexpression induces cell migration by enhancing the expression of vimentin and Snail in thyroid cancer cell lines." (PMID 33333840, 2020). "We also showed that TGF-β1 was able to induce Snail and vimentin expression in the Marca cell thyroid cancer line, indicating the induction of EMT in these cells, and this induction of EMT and stemness was significantly inhibited by celastro a natural inhibitor of neoplastic cells." (PMID 25076938, 2014). "Next, we checked the cytokeratin-18 and vimentin expression in thyroid cancer cell lines." (PMID 21556376, 2011). "The expression of β-catenin, Vimentin, and Slug were upregulated in cells with IKKα silencing, whereas downregulated in cells with IKKα overexpression, suggesting the differentiation promotion mediated by IKKα in thyroid cancer cells was accompanied by the inhibition of the EMT process." (PMID 33162555, 2021).
thyroid cancer (continued). "Also, in vitro E2 exposure enhances metastatic properties of both normal and thyroid cancer cell lines by targeting the expression of molecules involved in cell adhesion, migration, and invasiveness, such as β-catenin, E-cadherin, vimentin, and matrix metalloproteinases." (PMID 28588554, 2017). "Here, we observed that ZHX2 protein levels negatively correlated with the protein levels of vimentin and N-cadherin, and positively correlated with the protein levels of E-cadherin, indicating that ZHX2 restrains the migration of thyroid cancer cells." (PMID 35151335, 2022). "A few studies found that there was an aberrant expression of CTHRC1 in thyroid cancers, and CTHRC1 expression levels in PTC were significantly correlated with lymph node metastases, the expression of E-cadherin and vimentin." (PMID 33564303, 2021). "In thyroid carcinomas, EMT markers, including N-cadherin, Vimentin and Snail, are regulated by IL13RA2." (PMID 31585531, 2019). "Furthermore, neferine increased the relative protein expression of E-cadherin, while decreased the relative protein expression of N-cadherin and vimentin of IHH-4 and CAL-62 cells, suggesting that neferine hindered the EMT of thyroid cancer cells." (PMID 35794985, 2022). "In conclusion, the data reported here show a low expression of E-cadherin, unchanged level of vimentin, and reduction of the majority of EMT-TFs in PTC compared to normal thyroid tissues, which would suggest that thyroid cancer progression is characterized by an incomplete EMT." (PMID 34575184, 2021). "Interestingly, one of our patients had an unusual NTRK3 fusion with VIM on chromosome 10p3, a rare alteration observed only in thyroid cancers that has not been well characterized in the literature." (PMID 39295960, 2024). "DON treatment also significantly impaired the metastasis activity of thyroid cancer cells, not likely from EMT reversal, as epithelial and mesenchymal markers, including E-cadherin, N-cadherin, and Vimentin, were all decreased upon DON or JHU-083 treatment in vitro or in vivo." (PMID 38386265, 2024).
carcinosarcoma (27 papers, 2009 to 2025). A malignant tumor composed of a mixture of carcinomatous and sarcomatous elements. "Assessment of Trim24COE carcinosarcoma tumors by IHC revealed gain of vimentin, loss of E-cadherin, estrogen receptor (ER) and progesterone receptor (PR), and no over-expression of receptor tyrosine kinase erbB-2 (ERBB2)." (PMID 34508101, 2021). "Carcinosarcoma is characterized by the loss of intercellular adhesion, down-regulation of epithelial makers (cytokeratins), upregulation of mesenchymal markers [vimentin and smooth muscle actin (SMA)], increase in motility, invasiveness, and metastatic capabilities." (PMID 24625319, 2014). "Among the mesenchymal components, vimentin was frequently detected, while beta-catenin appeared in both epithelial and mesenchymal components of carcinosarcomas in four cases." (PMID 41367455, 2025). "Carcinosarcoma, a biphasic malignancy containing both epithelial and mesenchymal components, is characterized by concurrent CK and vimentin expression." (PMID 40746605, 2025). "In contrast, the KPOSE-AdCre cells are vimentin high and immune ‘cold’ and recreate carcinosarcoma histopathology." (PMID 40642792, 2025). "Histopathological study revealed high-grade carcinosarcoma, and immunohistochemistry showed diffuse positivity for vimentin, pan-cytokeratin (CK) and CK7, epithelial membrane antigen (EMA), and CK5/6." (PMID 38854258, 2024). "The patient was diagnosed with carcinosarcoma because the tumor cells were positive for both cytokeratin and vimentin." (PMID 31960152, 2020). "Ultrasound-guided fine needle aspiration of the abdominal soft tissue mass revealed malignant tumour cells, that were positive for vimentin; this confirmed recurrence in this known case of carcinosarcoma." (PMID 31678697, 2019). "Among both carcinosarcomas and metaplastic tumors, we observed dual expression of mesenchymal (Vimentin) and epithelial (Keratin-8) markers, which are mutually exclusive lineage markers in the normal gland." (PMID 23173005, 2012). "Final diagnosis of carcinosarcoma was confirmed by H & E staining and immunohistochemical analysis showing Vimentin (+), Cytokeratins (+) and EMA (+)." (PMID 21087479, 2010). "Immunostaining revealed a mutually exclusive pattern of expression of cytokeratin and vimentin in the carcinomatous and sarcomatous components, respectively, supporting the presence of a dual tumor cell population and confirming the diagnosis of carcinosarcoma." (PMID 32796551, 2020). "Furthermore, staining with vimentin, CD10, or caldesmon helps distinguish the mesenchymal component of primary carcinosarcoma." (PMID 41367455, 2025). "Conversely, carcinosarcoma demonstrates both epithelial and mesenchymal differentiation, with the mesenchymal component expressing markers like vimentin while lacking epithelial marker expression." (PMID 41357596, 2025). "In sarcomatoid carcinoma, the spindle cells express vimentin and epithelial tissue markers such as cytokeratin (CK), whereas in carcinosarcoma, the sarcomatous component does not express CK." (PMID 39301540, 2024). "Histopathological examination revealed a malignant tumour cells included epithelial components of carcinosarcoma, and were positive for vimentin and negative for cytokeratin (CK)." (PMID 31678697, 2019). "Sarcomatoid carcinomas can be differentiated from carcinosarcomas which immunohistochemically show cytokeratin and vimentin reactivity and are, therefore, not considered to be true carcinomas." (PMID 21143956, 2010). "The KPOSE-AdCre carcinosarcoma model is WT1 and HNF1β negative, vimentin high, and shows low T-cell infiltration and no B cells or TLSs." (PMID 40642792, 2025). "SMP30 was not merged with vimentin, indicating that SMP30 was not expressed in any of the myoepithelial cells in complex adenoma, benign mixed tumor, and carcinosarcoma." (PMID 33652881, 2021).
head and neck squamous cell carcinoma (27 papers, 2014 to 2025). A squamous cell carcinoma that arises from any of the following anatomic sites: lip and oral cavity, nasal cavity, paranasal sinuses, pharynx, larynx, and salivary glands. "Decrease of E-cadherin and gain of vimentin promoted tumor migration, leading to higher metastatic risk of head and neck squamous cell carcinoma patients." (PMID 31620368, 2019). "Additionally, it has been shown that not only the loss of KLK6 but also the loss of SOX2 expression induces cell motility via vimentin up-regulation and is an unfavorable risk factor for survival of head and neck squamous cell carcinoma." (PMID 28671620, 2017). "In-vitro arrays showed that areca nut extract treatment enhanced migration and invasion of head and neck squamous cell carcinoma (HNSCC) cells by upregulating cyclooxygenase-2 (COX-2)/vimentin expression, which is associated with poor survival of HNSCC patients." (PMID 36500264, 2022). "In head and neck squamous cell carcinoma (HNSCC), knocking down EphA2 in vitro leads to a reduction in the number of VM channels, and the expression of EphA2 and EMT-related markers such as Twist and Vimentin expression have a positive association." (PMID 32169087, 2020). "Overexpression of vimentin contributes to several cancers’ progression, invasion, and/or metastasis, including breast, ovarian, prostate, lung, colorectal cancers, tumors of the central nervous system and gastrointestinal tract, malignant melanoma, and also head and neck squamous cell carcinoma." (PMID 38611032, 2024). "In head and neck squamous cell carcinomas (HNSCCs), the expression of the long non-coding RNA (lncRNA) lnc-LCE5A-1 and lnc-KCTD6-3 was associated with reduced overall survival, while the ectopic expression of this lncRNA decreased Vimentin mRNA levels and impaired HNSCC cell migration in vitro." (PMID 38067168, 2023). "Inhibition of PTX3 has been shown to downregulate EMT-related molecules, such as vimentin and matrix metalloproteinase (MMP) 3, in head and neck squamous cell carcinoma cell lines." (PMID 39594709, 2024). "In this study, we used the human head and neck squamous cell carcinoma (HNSCC) SAS cells as a model and found that loss of cell–cell adhesion induced reactive oxygen species (ROS) generation and vimentin expression, both of which were required for SAS cell migration upon loss of cell–cell adhesion." (PMID 36446524, 2023). "In squamous cell carcinoma of the head and neck (SCCHN), E‐cadherin and vimentin are proved to be downstream target molecules of chemokine receptor 7 (CCR7)‐Pyk2, which may participate in the modulation of EMT, migration, and invasion of cancer cells." (PMID 31368612, 2019). "Previous studies have explored the correlation of ZEB2‐AS1 with EMT‐related markers in head and neck squamous cell carcinoma (HNSCC) and triple‐negative BC and showed a positive association between ZEB2‐AS1 and ZEB2/vimentin." (PMID 37088469, 2023).